SLC9A8 (solute carrier family 9 member A8)
Description:
Na(+)/H(+) antiporter. Mediates the electoneutral exchange of intracellular H(+) ions for extracellular Na(+) in 1:1 stoichiometry. Acts as an Na(+)/H(+) exchanger in the trans-Golgi. Contributes to the regulation of pH regulation of Golgi apparatus, and consequently, in protein trafficking and endosomal morphology. In germ cells, plays a crucial role in acrosome biogenesis and sperm development, probably by playing a role in the fusion of the Golgi-derived vesicles that form the acrosomal cap (By similarity). Can also be active at the cell surface of specialized cells. In the small intestine, at the cell membrane, plays a major physiological role in transepithelial absorption of Na(+) and regulates intracellular pH homeostasis of intestinal epithelial cells. Acts as an important regulator of mucosal integrity in the intestine and in the stomach, could mediate the pH fluctuation necessary for mucin exocytosis or assist membrane trafficking of other proteins (By similarity). Plays a role in photoreceptor survival and in the maintenance of intracellular pH homeostasis in retinal pigment epithelium (RPE cells) (By similarity).
Synonyms: NHE-8; KIAA0939; NHE8
Tractability: Antibody: UniProt places it where antibodies can reach, with high confidence; UniProt predicts a signal peptide or a membrane-spanning region; its Gene Ontology location is reachable by antibodies, with medium confidence. PROTAC: ubiquitination databases record sites on it; its protein half-life has been measured.
Gene: Protein-coding gene on chromosome 20 (49,812,713 to 49,892,242, forward strand). Ensembl gene ENSG00000197818.
Subcellular location: Golgi apparatus membrane; Golgi apparatus, trans-Golgi network membrane; Endosome, multivesicular body membrane; Apical cell membrane; Cytoplasmic vesicle, secretory vesicle, acrosome
Pathways (Reactome):
Transport of small molecules: Sodium/Proton exchangers
Gene Ontology:
Molecular function: potassium:proton antiporter activity; protein binding; sodium:proton antiporter activity; antiporter activity
Biological process: Golgi lumen acidification; proton transmembrane transport; regulation of intracellular pH; sodium ion transmembrane transport; acrosome assembly; monoatomic cation transport; potassium ion transmembrane transport; regulation of pH; sodium ion transport; transmembrane transport
Cellular component: apical plasma membrane; Golgi membrane; multivesicular body membrane; trans-Golgi network membrane; acrosomal vesicle; Golgi apparatus; membrane
Genetic constraint (gnomAD): Loss-of-function variants: 30 observed, 40.28 expected, observed/expected ratio (o/e) 0.74, 90% interval 0.56 to 1.01. The upper end of that interval is the gene's LOEUF score, 1.01, which puts it in group 4 of 6, group 1 being the genes least tolerant of losing a copy. Missense variants: 494 observed, 627.38 expected, observed/expected ratio (o/e) 0.79, 90% interval 0.73 to 0.85. Synonymous variants: 235 observed, 249.92 expected, observed/expected ratio (o/e) 0.94, 90% interval 0.85 to 1.05.
Homologues: Orthologues: chimpanzee SLC9A8 (99% identical), macaque SLC9A8 (99% identical), pig SLC9A8 (98% identical), guinea pig SLC9A8 (97% identical), mouse Slc9a8 (96% identical), rat Slc9a8 (94% identical), dog SLC9A8 (94% identical), tropical clawed frog slc9a8 (90% identical), zebrafish slc9a8 (85% identical), rabbit SLC9A8 (82% identical), Drosophila melanogaster Nhe1 (55% identical), Caenorhabditis elegans nhx-8 (40% identical). Paralogues in human: SLC9A9 (33% identical), SLC9A6 (33% identical), SLC9A7 (33% identical), SLC9A5 (27% identical), SLC9A1 (26% identical), SLC9A2 (25% identical), SLC9A3 (24% identical), SLC9A4 (24% identical), SLC9C1 (15% identical), SLC9C2 (13% identical).
Diseases named in the same sentence as SLC9A8 in open-access papers:
SLC9A8 is named in the same sentence as 35 diseases in open-access papers, as found by Europe PMC text mining. Sharing a sentence is not in itself a finding about the gene and the disease. The quoted sentences say what the papers report.
dementia (1 paper, 2023). Loss of intellectual abilities interfering with an individual's social and occupational functions. "Together, these reports and our results support that certain flavonoids can mitigate dementia risk via an SLC9A8 function in membrane trafficking, perhaps in the gut." (PMID 36771351, 2023). "SLC9A8 is among four loci identified as contributing to the genotype–beta diversity of the gut microbiome, which invokes the gut–brain axis as a conveyor of dementia." (PMID 36771351, 2023).
ovarian carcinoma (1 paper, 2021). A malignant neoplasm originating from the surface ovarian epithelium. "In addition, several other potentially interesting targets of YTHDF2 in ovarian cancer have been identified, such as the putative tumor suppressors TRERF1, ZDHHC14, DIS3L, Vps18, NOD1, and SLC9A8." (PMID 33658012, 2021).
retinal degeneration (1 paper, 2015). Degeneration of the retina. "From a forward genetic study of new retinal degeneration mouse mutations, we have found that mutations of the SLC9A8 gene, which encodes the sodium/proton exchanger 8 (NHE8), lead to slow photoreceptor cell death." (PMID 25791178, 2015).
cancer (4 papers, 2019 to 2023). A tumor composed of atypical neoplastic, often pleomorphic cells that invade other tissues. "Data from genome-wide association studies (GWAS) in humans also found polymorphism in the SLC9A8 gene, which encodes NHE8, to be critically linked to cancer progression." (PMID 36901695, 2023).
SLC9A8 also shares sentences with these, for which no sentence is quoted: colitis (6 papers); infertile (5); Globozoospermia (3); tumor (3); congestive heart failure (2); gastric ulcer (2); ulcerative colitis (2); adenoma (1); ankylosing spondylitis (1); cardiovascular diseases (1); colon cancer (1); colonitis (1); colorectal tumors (1); Crohn disease (1); diabetes (1); dilated cardiomyopathy (1); Down syndrome (1); heart failure (1); Huntington disease (1); hypertrophic cardiomyopathy (1); leukemia (1); lupus (1); melanoma (1); mental retardation (1); multiple sclerosis (1); primary sclerosing cholangitis (1); psoriasis (1); pulmonary edema (1); renal cell carcinoma (1); schizophrenia (1).
A further 1 disease shares a sentence with SLC9A8 in 1 paper.